NELL2 (neural EGFL like 2)
Description:
Plays multiple roles in neural tissues, regulates neuronal proliferation, survival, differentiation, polarization, as well as axon guidance and synaptic functions. Plays an important role in axon development during neuronal differentiation through the MAPK intracellular signaling pathway (By similarity). Via binding to its receptor ROBO3, plays a role in axon guidance, functioning as a repulsive axon guidance cue that contributes to commissural axon guidance to the midline. Required for neuron survival through the modulation of MAPK signaling pathways too. Involved in the regulation of hypothalamic GNRH secretion and the control of puberty (By similarity). Epididymal-secreted protein that signals through a ROS1-pathway to regulate the epididymal initial segment (IS) maturation, sperm maturation and male fertility.
Synonyms: NRP2
Tractability: Antibody: UniProt places it where antibodies can reach, with medium confidence; UniProt predicts a signal peptide or a membrane-spanning region; its Gene Ontology location is reachable by antibodies, with medium confidence.
Gene: Protein-coding gene on chromosome 12 (44,508,274 to 44,921,889, reverse strand). Ensembl gene ENSG00000184613.
Subcellular location: Secreted
Subcellular location (Human Protein Atlas): Vesicles; Predicted to be secreted
Pathways (Reactome):
Developmental Biology: Regulation of commissural axon pathfinding by SLIT and ROBO
Gene Ontology:
Molecular function: calcium ion binding; identical protein binding; protein binding; heparin binding; protein kinase C binding
Biological process: commissural neuron axon guidance; fertilization; neuron cellular homeostasis
Cellular component: cytoplasm; extracellular region; non-collagenous component of interstitial matrix
Genetic constraint (gnomAD): Loss-of-function variants: 35 observed, 93.67 expected, observed/expected ratio (o/e) 0.37, 90% interval 0.28 to 0.5. The upper end of that interval is the gene's LOEUF score, 0.5, which puts it in group 2 of 6, group 1 being the genes least tolerant of losing a copy. Missense variants: 820 observed, 978.69 expected, observed/expected ratio (o/e) 0.84, 90% interval 0.79 to 0.89. Synonymous variants: 324 observed, 340.07 expected, observed/expected ratio (o/e) 0.95, 90% interval 0.87 to 1.04.
Homologues: Orthologues: chimpanzee NELL2 (99% identical), macaque NELL2 (99% identical), pig NELL2 (98% identical), dog NELL2 (96% identical), guinea pig NELL2 (96% identical), mouse Nell2 (94% identical), rat Nell2 (94% identical), rabbit NELL2 (92% identical), tropical clawed frog nell2 (81% identical), zebrafish nell2b (66% identical), zebrafish nell2a (62% identical). Paralogues in human: NELL1 (55% identical).
Diseases named in the same sentence as NELL2 in open-access papers:
NELL2 is named in the same sentence as 49 diseases in open-access papers, as found by Europe PMC text mining. Sharing a sentence is not in itself a finding about the gene and the disease. The quoted sentences say what the papers report.
ependymoma (4 papers, 2016 to 2022). A WHO grade II, slow growing tumor of children and young adults, usually located intraventricularly. "The aim of this study was to analyze the status of chromosome 1q, TNC, LAMA2, and NELL2 expression in a series of pediatric PF ependymomas in terms of their frequency, associations among themselves and clinical parameters, as well as their prognostic impact." (PMID 27550150, 2016). "Therefore, we have analyzed the status of chromosome 1q, TNC, LAMA2, and NELL2 expression in a series of pediatric PF ependymomas in terms of their frequency, associations among themselves, and clinical parameters, as well as their prognostic impact." (PMID 27550150, 2016). "In our analysis average dCt values for LAMA2 and NELL2 genes expression were higher in grade III ependymomas what indicated that more aggressive tumors showed lower expression values." (PMID 27390862, 2016). "We identified three major clusters, with the NELL2+/LAMA2− pattern overlapping with PFB ependymomas, and the remaining two clusters overlapping with PFA ependymomas." (PMID 34314101, 2021). "In a previously analyzed cohort of PF ependymomas LAMA2 was expressed in 67 % of the tumors in patients ≤ 21 years, thus in a similar percentage, however 10 % of these patients expressed also NELL2." (PMID 27550150, 2016).
atopic dermatitis (3 papers, 2017 to 2023). "Nell2, on the other hand, is reported to be specifically expressed in the epidermis (keratinocytes) of patients suffering from atopic dermatitis." (PMID 28587635, 2017). "In accordance with the results of the mRNA expression obtained for primary keratinocytes, atopic dermatitis biomarkers such as NELL2, CA2 and CCL26 were significantly elevated in skin models m2 and m3 stimulated with TH2 cytokines (p < 0.05, p < 0.001, respectively)." (PMID 36615633, 2023). "Furthermore, the upregulation of disease-associated biomarkers, such as NELL2, CA2 and CCL26, indicates the prevalence of an immune response in the atopic dermatitis skin model." (PMID 36615633, 2023). "Moreover, NELL2 (neural epidermal growth factor-like 2) and CA2 (carbonic anhydrase 2) that are representative of atopic dermatitis and differentiates from psoriasis were also upregulated." (PMID 33806193, 2021).
benign prostate hyperplasia (3 papers, 2007 to 2023). "At the top of the list of proteins modified by FOXO3 genotype is neural epidermal growth factor-like like 2 (NELL2) that causes cell proliferation and inhibition of apoptosis when overexpressed in benign prostate hyperplasia." (PMID 36881352, 2023). "It is reported that the mRNA expression of NELL2 is up-regulated in benign prostate hyperplasia and prostate cancer." (PMID 29439675, 2018). "Nell2 is a secreted epidermal growth factor family member; no function has been described for this protein, but it was shown to be over-expressed in benign prostatic hyperplasia." (PMID 17922897, 2007).
Ewing sarcoma (3 papers, 2021 to 2025). A small round cell tumor that lacks morphologic, immunohistochemical, and electron microscopic evidence of neuroectodermal differentiation. "While studying the impact of NELL2 silencing on Ewing sarcoma, we found that suppression of NELL2 signaling induces the expression of endogenous retroviruses (ERVs) and LINE-1 retrotransposons, an interferon response, and growth arrest." (PMID 34966479, 2021). "Upon further investigation of the impact of NELL2 signaling on Ewing sarcoma, we found that the suppression of NELL2 signaling induces the expression of endogenous retroviruses (ERVs) and LINE-1 retrotransposons and an interferon response in Ewing sarcoma." (PMID 34966479, 2021). "We identified two populations of cells in Ewing sarcoma, NELL2highCD133highEWS-FLI1high and NELL2lowCD133lowEWS-FLI1low, which display phenotypes consistent with high and low NELL2 signaling, respectively." (PMID 34966479, 2021). "We recently reported that Ewing sarcoma depends on the autocrine signaling mediated by a cytokine, NELL2." (PMID 34966479, 2021). "NELL2, CD133, and EWS-FLI1 positively regulate each other and upregulate the BAF complexes and cell proliferation in Ewing sarcoma." (PMID 34966479, 2021).
bladder cancer (2 papers, 2018 to 2025). "LC2 also exhibited elevated expression of NEB, a gene more commonly linked to neuroendocrine and small cell bladder cancer, as well as NELL2, which has been implicated in promoting cell viability and proliferation in bladder cancer cells." (PMID 41425537, 2025). "This included strong upregulation of cancer‐testis antigens (MAGEA3, MAGEA6, MAGEA10) and neuroendocrine‐associated genes such as NEB and NELL2, features linked to higher tumour grade, invasion and lineage plasticity in bladder cancer." (PMID 41425537, 2025). "In addition, NELL2 is regarded as the potential biomarker for bladder cancer." (PMID 29439675, 2018).
COVID-19 (2 papers, 2021 to 2024). A disease caused by infection with severe acute respiratory syndrome coronavirus 2. "In line with our findings, NELL2 is downregulated in patients with severe and mild COVID-19 in comparison to controls." (PMID 38575325, 2024). "For example, NELL2, which was involved in the regulation of hypothalamic GNRH secretion and the control of puberty, lowers the risk of COVID-19 hospitalization and SARS-COV2 infection." (PMID 38575325, 2024). "Both, severe and mild COVID-19 in comparison to controls shared neutrophil-specific CD177 and HP expression among the most upregulated DEGs, as well as lymphocyte-associated genes such as ABLIM1, NELL2, RCAN3, RORC, BACH2, and KLRB1, among the downregulated genes." (PMID 33441124, 2021).
embryonic carcinoma (2 papers, 2014 to 2025). "In this study, we identified NELL2 function during neural differentiation of mouse embryonic carcinoma P19 cells." (PMID 24465772, 2014). "In this study, we found that NELL2 plays an important role in neuronal differentiation of P19 mouse embryonic carcinoma cells." (PMID 24465772, 2014).
gastric cancer (2 papers, 2020 to 2022). A primary or metastatic malignant neoplasm involving the stomach. "In this study, we found that higher tRF-3017A were associated with significantly higher lymph node metastasis in gastric cancer patients and the tRF-3017A may play a role in promoting the migration and invasion of gastric cancer cells by silencing tumor suppressor NELL2." (PMID 33665159, 2020). "In gastric cancer (GC), tRF-3017A can bind to Argonautes (AGO) protein to form RISC and downregulate the expression of the tumor suppressor gene neural EGFL like 2 (NELL2), thus affecting the migration, invasion, and other functions of GC cells." (PMID 35658952, 2022).
glioma (2 papers, 2021 to 2022). A benign or malignant brain and spinal cord tumor that arises from glial cells (astrocytes, oligodendrocytes, ependymal cells). "Differentially expressed genes (DEGs) in the glioma samples relative to normal samples were screened from the GEO database, and five prognostically relevant BM-related genes, including NELL2, UNC5A, TNC, CSPG4, and SMOC1, were selected using Cox regression analyses for the risk score model." (PMID 36292695, 2022).
non-small cell lung carcinoma (2 papers, 2022 to 2025). A group of at least three distinct histological types of lung cancer, including non-small cell squamous cell carcinoma, adenocarcinoma, and large cell carcinoma. "For example, E2F1 transcriptional activation of neural epidermal growth factor-like 2 (NELL2) accelerates the progression of non-small cell lung cancer." (PMID 36249071, 2022).
prostate carcinoma (2 papers, 2018 to 2020). A carcinoma that arises from epithelial cells of the prostate gland. "The reference-free diagnostic panel used the ratio of relative expression of three mRNAs that are overexpressed (FOLH1, XBP1 and HPN) to five mRNAs that are underexpressed (ITSN1, GSTM4, LTBP4, NELL2, and CFD) in prostate cancer compared to normal tissue." (PMID 33172003, 2020). "However, two of the mRNAs, LTBP4 and NELL2, could not be measured in several prostate cancer and benign control samples." (PMID 33172003, 2020).
psoriasis (2 papers, 2021 to 2022). An autoimmune condition characterized by red, well-delineated plaques with silvery scales that are usually on the extensor surfaces and scalp. "Further research will need to be undertaken to establish the contribution of NELL2 in psoriasis, but the overproduction of NELL2 in PS+T may offer an explanation for the hyper-innervation that is found in psoriasis." (PMID 36139479, 2022). "More studies are needed to establish whether NELL2 might contribute to the pathogenesis of psoriasis." (PMID 36139479, 2022).
renal cell carcinoma (2 papers, 2021 to 2024). "NELL2 (neural EGFL like 2) for example, expressed in the neural tube and involved in neural development, has also been described as a tumor suppressor since it is enriched in normal nerve cells compared with nervous system tumors and inhibits cancer cell migration in renal cell carcinoma." (PMID 34445617, 2021).
Alzheimer disease (1 paper, 2022). A progressive, neurodegenerative disease characterized by loss of function and death of nerve cells in several areas of the brain leading to loss of cognitive function such as memory and language. "We also identified multiple neuronal-associated diseases such as Alzheimer’s disease, neurodevelopmental disorder, and sensorimotor neuropathy, consistent with our observation that NELL2 is abundant in post-mitotic neurons of the brain and spinal cord." (PMID 35265611, 2022).
autism (1 paper, 2010). Persistent deficits in social interaction and communication and interaction as well as a markedly restricted repertoire of activity and interest as well as repetitive patterns of behavior. "The six candidate genes sequenced, CNTN1, FOXJ2, GRIN2B, NAB2, NELL2 and SRGAP1, were selected based on their putative functions, and their relationships to genes potentially involved in the pathology of language impairments, auditory processing deficits, autism and dyslexia." (PMID 20345892, 2010).
clear cell carcinoma (1 paper, 2020). "Existing studies have shown that NELL2 is enriched in paracancer tissue and can inhibit clear cell carcinoma metastasis." (PMID 33665159, 2020).
Intellectual disability (1 paper, 2020). "The intragenic microdeletion of DCP139 within NELL2 strongly suggests that it is the more likely candidate for the intellectual disability seen in the patient DCP139." (PMID 31963867, 2020).
kidney cancer (1 paper, 2015). Primary or metastatic malignant neoplasm involving the kidney. "Interestingly, a recent study showed that NELL2 is a target gene for HNF4α, which is frequently lost in kidney cancer, and that expression of NELL2 contributes to HNF4α mediated inhibition of proliferation in kidney cells." (PMID 26624623, 2015).
male infertility (1 paper, 2024). The inability of the male to effect fertilization of an ovum after a specified period of unprotected intercourse. "An intriguing question is whether dysfunction of NELL2, NICOL, or ROS1 causes male infertility, although mutations in these genes have not been identified as causal factors in humans." (PMID 38169386, 2024).
Osteopenia (1 paper, 2025). Osteopenia is a term to define bone density that is not normal but also not as low as osteoporosis. "In this study, we observed that NELL2 was diminished in the bone of aged and ovariectomized (OVX) mice, as well as in the serum of osteopenia and osteoporosis patients." (PMID 40210857, 2025).
osteosarcoma (1 paper, 2021). A usually aggressive malignant bone-forming mesenchymal neoplasm, predominantly affecting adolescents and young adults. "NELL1 and NELL2, which act as suppressors in various types of cancer including osteosarcoma, were identified as proteins that interact with ANO5." (PMID 34238763, 2021). "In previous studies, NELL1 and NELL2, which act as tumor suppressors, were downregulated in a variety of cancers including osteosarcoma." (PMID 34238763, 2021). "Furthermore, confocal microscopy demonstrated that ANO5 was colocalized with NELL1 and NELL2 in osteosarcoma cells." (PMID 34238763, 2021). "Finally, rescue experiments showed that knockdown of NELL1 or NELL2 reversed the inhibitory effects of ANO5 knockdown on osteosarcoma cell proliferation and migration." (PMID 34238763, 2021). "To determine whether NELL1 and NELL2 were involved in ANO5-induced osteosarcoma, we inhibited NELL1 or NELL2 expression in ANO5 knockdown cells." (PMID 34238763, 2021). "In this study, we found that ANO family member ANO5 was highly expressed in osteosarcoma tissues and cell lines and that it promoted the proliferation and metastasis of osteosarcoma cells by increasing the degradation of NELL1 and NELL2." (PMID 34238763, 2021). "ANO5 expression was elevated in osteosarcoma and promoted the development of osteosarcoma cells by increasing degradation of the tumor suppressors NELL1 and NELL2." (PMID 34238763, 2021). "Taken together, these findings demonstrate that suppression of ANO5 decreased osteosarcoma cell proliferation and increased NELL1 and NELL2 expression in vivo." (PMID 34238763, 2021). "We found that ANO5 promoted the proliferation and metastasis of osteosarcoma by increasing the degradation of NELL1 and NELL2." (PMID 34238763, 2021). "The STRING interaction network for ANO5 indicated that it interacted with NELL1 and NELL2, suggesting that these proteins may play a role in ANO5-induced proliferation and metastasis in osteosarcoma." (PMID 34238763, 2021). "Moreover, a subcutaneous tumor transplantation model revealed that ANO5 knockdown reduced osteosarcoma cell proliferation and increased NELL1 and NELL2 expression in vivo." (PMID 34238763, 2021).
posterior fossa ependymoma (1 paper, 2016). A high grade ependymoma that is located within the posterior fossa. "Together with miRNA analysis, we conducted expression studies of LAMA2 and NELL2 genes, which have been suggested as a possible prognostic factors for children with posterior fossa ependymomas." (PMID 27390862, 2016).
Pruritus (1 paper, 2025). Pruritus is an itch or a sensation that makes a person want to scratch. "Similarly, neuron-specific Nel-like protein 2 (NELL2), prominently expressed in the epidermis of AD patients, has been linked to the pruritus characteristic of the disease, offering a potential target for diagnostic and therapeutic strategies." (PMID 40141720, 2025).
renal carcinoma (1 paper, 2022). A carcinoma arising from the epithelium of the renal parenchyma or the renal pelvis. "There has been evidence that NELL2 is abundant in normal nerve cells, relative to nervous system tumours, and it blocks the proliferation in renal cancer." (PMID 35957621, 2022).
scrapie (1 paper, 2012). A fatal disease of the nervous system in sheep and goats, characterized by pruritus, debility, and locomotor incoordination. "In accordance with this, we found here that neural tissue-specific epidermal growth factor-like repeat domain-containing protein) NELL2 is overexpressed in preclinical scrapie." (PMID 22897917, 2012).
spinocerebellar ataxia type 7 (1 paper, 2020). "Moreover, the same study showed that NELL2 interacts with ATAXIN7 (ATXN7, MIM 607640), the causative gene for spinocerebellar ataxia type 7 (SCA7)." (PMID 31963867, 2020).
tuberculosis (1 paper, 2022). A chronic, recurrent infection caused by the bacterium Mycobacterium tuberculosis. "The levels of NELL2 were low before treatment and tended to increase after anti-tuberculosis treatment." (PMID 36494747, 2022). "The level of NELL2 in the TBM group was lower than that in the control group (P < 0.05), and the level of NELL2 showed an increasing trend after anti-tuberculosis treatment in the TBM group." (PMID 36494747, 2022). "Therefore, in this study, the differences in NELL2 in CSF between the TBM disease group and the control group and the changes in NELL2 in the TBM group after anti-tuberculosis treatment were explored by Western blotting." (PMID 36494747, 2022).